TNF (tumor necrosis factor)
Diseases named in the same sentence as TNF in open-access papers (continued):
Sharing a sentence is not in itself a finding about the gene and the disease.
Allergy (continued). "Similar as in the comparison to allergy groups, the relationship between synbiotics and IL-17 signaling can probably be explained by the large overlap with TNF signaling." (PMID 40929127, 2025). "Anti-allergic properties of ethanolic extracts of fruits and leaves of M. citrifolia outlined its inhibitory effects on IL-1β and TNF-α in dinitrofluorobenzene (DNFB) induced allergy in mice ear, thereby reducing ear swelling." (PMID 40154100, 2025). "Proinflammatory cytokines with high importance in developing allergic reactions: IL-1β, IL-6, TNF-α, TGF-β, and GM-CSF were selected for the study." (PMID 39881795, 2025). "Mast cells appear to be a critical source of TNF-α in allergic diseases, and urinary IL-9 and TNF-α are simultaneously elevated in human AIN." (PMID 40091836, 2025). "TNF plays a known role in allergic sensitization and is typically elevated during late-phase allergic reactions, particularly by promoting neutrophil recruitment." (PMID 41301750, 2025). "Macrophages can differentiate into the M1 type, leading to increased secretion of inflammatory factors, such as NO, IL-6, and TNF-α, which ultimately contribute to the progression of allergic diseases." (PMID 39757930, 2025). "This is interesting as an in vitro study has shown that synthesis of lactose in lactating mammary epithelial cells is inhibited by pro-inflammatory cytokines TNF-α, IL-1β and IL-6, all of which play roles in allergy." (PMID 39458508, 2024). "Other mast cell mediators such as IL-3, IL-5, IL-8, and tumor-necrosis factor (TNF) recruit eosinophils, neutrophils, and Th2 cells, and they also interact with other tissue cells to start late-phage allergic reaction." (PMID 39195277, 2024). "Cytokine recruitment, namely, IL-4, IL-5, IL-6, and TNF-α, encourages IgE synthesis in the first phases of an allergic reaction." (PMID 38835658, 2024). "The initiating node of cluster 1 is TNF, which is a pivotal mediator in regulating immune responses involved in infection control, autoimmune conditions, allergic diseases, and antitumor activity." (PMID 39771032, 2024). "TNF can promote the migration of inflammatory cells, such as eosinophils and neutrophils, to the inflammatory site, aggravate allergic reactions, promote the production of cytokines, enhance the activity of immune cells, and lead to a stronger immune response." (PMID 38533318, 2024). "An inflammatory cytokine TNF-α has been shown to be overexpressed in this type of allergic reaction, whereas the TGF-β1 receptor activity and TGF-β ligand expression were shown to be decreased." (PMID 39085570, 2024). "IL-13 is a Th2 cytokine in the immune system thought to play an important role in the development of allergies, although it has also been ascribed anti-inflammatory roles, inhibiting different pro-inflammatory mediators such as IL-1β and TNF-α." (PMID 37373554, 2023). "The HWE equilibrium law was followed by the frequency distributions of the following polymorphisms in allergy patients: CYSLTR1 rs320995, GSDMB rs7216389, GPIIIa rs5918, GP1BA rs6065, PEAR1 rs12041331, PAI-1 rs1799762, and TNF-α rs1800629 (p > .05)." (PMID 36911417, 2023). "Here, we show that GJExCR treatment reduced the Th2-mediated immune response in OVA-induced allergy, including dampening of IL-4, IL-5, IL-10, IL-13, TNF-α, INF-γ, chemokine, and IgE expression, in both serum and spleens." (PMID 36980282, 2023). "The second study also found a decrease in clinical symptoms of allergy (dose-dependent) as well a a decrease in IgE, mouse mast cell protease (mMCP)-1, and TNF-α levels in the olive oil group (p < 0.01)." (PMID 37571232, 2023). "Luteolin can inhibit the FcεRΙ- and MrGPrx2-mediated allergic reaction in vivo and in vitro, and reduce the serum levels of histamine, TNF-α, MCP-1, IL-8 and IL-13 in mice." (PMID 36611103, 2023).
Allergy (continued). "Apart from the release of preformed mediators, the release of de novo synthesized inflammatory mediators such as TNF-α, IL-6, IL-8, and IL-4 by activated MC in a prolonged allergic reaction was well-reported in previous studies." (PMID 37667314, 2023). "Antihistamines alleviate symptoms of allergies through inhibition of histamine receptors which have been theorized to induce TNF-α-stimulated accumulation of pro-inflammatory cytokines." (PMID 36552336, 2022). "TNF-α plays a pivotal role in the pathogenesis of allergies and has been reported to contribute to both the early and late phases of allergy development." (PMID 36235405, 2022). "Tumor necrosis factor-α (TNF-α) is a pleiotropic Th1 cytokine, which plays a role in the pathogenesis of inflammatory diseases, including allergy." (PMID 36078171, 2022). "Our data show that the concentration of TNF-alpha was increased in patients with IgE-mediated allergy and slightly decreased in participants with delayed-type hypersensitivity when compared to the control group." (PMID 35805534, 2022). "MSCs treated with IFN-γ/TNF-α showed the modulating effect on Th9 cells contributing to the development of allergy by involving ILC2 activation, IgE production, eosinophil recruitment into airway." (PMID 35821386, 2022). "PPAR-γ agonists reduced the expression of TNF-α and IL-4 through down-regulation of NF-κB activation in mast-cell-related allergic diseases." (PMID 35807237, 2022). "Although infection is the primary cause of fever, endogenous heat sources such as IL-1β, TNF, IL-6, and PTGS2-induced prostaglandins also act on the thermoregulatory centers of allergic diseases." (PMID 35855823, 2022). "IL-6 had been defined as a modulate the adaptive immune response during early T-cell activation and TNF-α, which is a major effector cytokine in allergic reaction and improves mediator expression and cytokine in mast cells." (PMID 35200662, 2022). "TNF-α is an important inflammatory agent in the pathological development of allergic diseases, so the potential for treatment with TNF-α targeting agents has recently been considered to treat allergic marches." (PMID 35130903, 2022). "The TNF-α level was higher in Der p-induced allergy in mice and was significantly reduced by Dex and YGW (0.5 g/kg) treatments." (PMID 34070764, 2021). "TNF-α and IL-4 play critical roles in activating immune cells to produce other cytokines and IgE antibodies that aggravate allergic reactions." (PMID 34576749, 2021). "AD is recognized as a T helper 2 (Th2)–mediated allergic disease, accompanied by increases in cytokines such as tumor necrosis factor α (TNFα), interleukin 4 (IL-4), and IL-17." (PMID 33708782, 2021). "The effect of A. cepa supplementation (500 mg twice a day) on 419 cases with respiratory and allergic diseases showed a reduction in TNF-α and IL-6." (PMID 34552650, 2021). "TNF‐α promotes inflammation caused by neutrophils and T cells, leukocyte infiltration, and chemotaxis, while mast cells activate TNF‐α secretion, which plays a key role in allergic reactions." (PMID 34092045, 2021). "A subpopulation identified as Th cells (sTh#1) was significantly differing between allergy groups and the control group in the co-expression of TNF-α and IL-17A." (PMID 32698761, 2020). "TNF-α is one of the well-known proinflammatory cytokines and its inhibition is considered a viable strategy for preventing the allergy." (PMID 32033291, 2020). "Most striking was the decreased (co) expression of TNF-α in numerous cell clusters in the two allergy groups compared to the controls." (PMID 32698761, 2020). "Inflammatory cytokines including tumor necrosis factor (TNF)-α, interleukin (IL)-1β, IL-4, and IL-6 support a chronic phase of allergy, enhancing T cell activation or B cell survival." (PMID 32063904, 2020).
Allergy (continued). "On the basis of the mouse model, we found viridicatol to alleviate the allergy symptoms; decrease the levels of specific immunoglobulin E, mast cell protease-1, histamine, and tumor necrosis factor-α; and promote the production of interleukin-10 in the serum." (PMID 33081290, 2020). "IL-6 had been defined to modulate the adaptive immune response during early T cell activation, and TNF-α, which is a major effector cytokine in allergic reaction, improves mediator expression and cytokines in mast cells." (PMID 33256200, 2020). "High levels of TNF-α on 35th day imply its major role in the pathogenesis of allergy and its contribution to allergy development both in the early and late stages." (PMID 31694050, 2019). "Univariate analysis indicated that usage of immunosuppressive drugs, TNF-α inhibitors, and history of food or drug allergy were significantly related with TB-IRIS." (PMID 31905985, 2019). "Meanwhile, the late phase of an allergic reaction occurring hours after sensitisation will trigger the release of cytokines such as IL-4, IL-5, IL-9, IL-13, TNF-α and IFN-γ that will recruit inflammatory cells and further bring about mast cell degranulation." (PMID 31829185, 2019). "In human macrophages, DEHP treatment increases the production of inflammatory cytokines, such as TNF-α, IL-1β, IL-8, and IL-6, which induces the inflammatory response during allergic reactions." (PMID 31297340, 2019). "It is possible that endogenously derived TNF-α plays a role in the development of allergies through inflammatory processes at the epithelial barrier of the gut." (PMID 30410548, 2018). "TNF is reported to play significant role in the pathogenesis of allergy and contributes to both early and late stages of allergy development." (PMID 30473698, 2018). "Elevated TNF levels in severe allergy have been shown to contribute to the epithelial barrier dysfunction by upregulating the adhesion molecules (p120, E-cadherin) and increasing the endothelial permeability to allergens." (PMID 30473698, 2018). "Infliximab, the chimeric monoclonal anti-TNF, showed significantly, reduced pathological inflammation in allergy model." (PMID 30473698, 2018). "Studies have shown that in an allergy model, etanercept attenuates allergic lung inflammation while in allergic asthma it can even reverse the inhibitory activity of TNF onto Tregs." (PMID 30473698, 2018). "Subsequently, depending on the cytokine milieu including TNF, DCs would activate distinct T cell responses, which in allergy corresponds primarily to a Th2 response." (PMID 30473698, 2018). "Due to its important role in allergy manifestations, TNF has been evaluated as a target for therapy and findings have led to the discovery of a more prominent role of TNFR2 in the pathogenesis of allergy." (PMID 30473698, 2018). "TNFR2 signaling is attributable to the immunosuppressive effects of TNF and thus is protective against allergy." (PMID 30473698, 2018). "Mediators such as cytokines (IL-4, TNF-α, etc.)from the cells are involved in the late phase reaction of allergy." (PMID 30618741, 2018). "Tumor necrosis factor-alpha (TNF) is a pleiotropic cytokine, which is thought to play a major role in the pathogenesis of inflammatory diseases, including allergy." (PMID 30473698, 2018). "Although it is well established that TNF plays a prominent role in establishment and maintenance of allergy, treatment with its antagonist in allergy population shows to be inefficient although they successfully attenuate the symptoms in allergy model." (PMID 30473698, 2018). "This is evident when allergy manifestations are inhibited in TNF-knockout (KO) mice as well as with anti-TNF treatments." (PMID 30473698, 2018). "Regulation of TNF on Tregs, DCs and MDSCs for protective immune response against allergic reactions." (PMID 30473698, 2018).
Allergy (continued). "Release of IL-4 primarily regulates hyper-production of IgE, and expression of TNF-α and IL-6 stimulate the synthesis of acute phase response protein, which attenuates secretion of IgE and disruption of skin barrier function during allergic reactions." (PMID 28358324, 2017). "Inflammatory cytokines such as TNF-α, IL-1β, and IL-4 play crucial roles in prompting and sustaining chronic allergy." (PMID 26068872, 2015). "Since B cell levels of ADAM10, ADAM17, and TNF mRNA expression were clearly different in control and allergic patients; and allergy is a Th2-dominated disorder; we sought to confirm our results in classic Th1 and Th2 prone mouse strains." (PMID 25933166, 2015). "In 2 cases treatment with TNF-blockers was stopped after a short time because of side effects (skin infection, allergic reaction) and in further 2 cases treatment was unsuccessful." (PMID 26088861, 2015). "Analysis of tryptase concentration, histamine, arachidonic acid derivatives, interleukins, tumor necrosis factor, complement, eosinophil, and total and specific immunoglobulin E levels is recommended to specify the status of allergic reaction." (PMID 25435880, 2014). "We investigated the anti-allergic activity of streptochlorin by monitoring the production of allergy-associated cytokines, such as IL-4, INF-γ, and TNF-α, in the ear lobes after DNFB treatment." (PMID 24086321, 2013). "An additional component of this study was a direct comparison of the cytokines induced by the allergy-related mediators IL-4/IL-13 with TNF-α in two surface ocular cell types, HConEpiC and HConF." (PMID 23878502, 2013). "In patients with both types of allergy i.e. skin and rhinitis, there was a positive correlation of IL-5 with IL-10 and that of IL-6 with TNF α." (PMID 20616938, 2010). "One TNF antagonist-naïve patient experienced a serious allergic reaction, which was the only one reported in the STEREO study." (PMID 20553600, 2010). "The effect of air pollution from traffic on childhood allergy appears to be modified by GSTP1 and TNF variants, supporting a role of genes controlling the antioxidative system and inflammatory response in allergy." (PMID 18709160, 2008). "In addition, TNF-α has also been identified as playing a role in the inflammatory response in allergies, which are related to air pollution." (PMID 40399383, 2025). "SCFAs directly influence immune responses by stimulating immune cells, promoting neutrophil recruitment, inhibiting NF-κB and tumor necrosis factor alpha (TNFα), supporting B cell differentiation, and regulating systemic immune responses to protect against allergic diseases and neuroinflammation." (PMID 40438731, 2025). "TNF-α is a crucial cytokine responsible for the recruitment of leukocytes, including neutrophils and eosinophils, to inflammatory sites, thereby contributing to the progression of late-phase allergic reactions." (PMID 39596204, 2024). "A study has demonstrated that puerarin has been observed to inhibit the activation of the NF-kappa B pathway and the production of TNF-α in peripheral blood mononuclear cells of asthmatic patients, suggesting its potential protective role against allergic diseases." (PMID 38792575, 2024). "Also, studies have reported that LP improves neuroinflammation, and prevents the development of allergies by modulating the host immune response.LB had a relatively small role in anti-inflammatory, mainly manifested in the downregulation of TNF-α." (PMID 37217991, 2023). "Histamine is responsible for inflammation in allergic reactions in general, but bacteria-metabolized histamine has been shown to inhibit the production of pro-inflammatory cytokines such as TNF-α in vivo and IL-1 and IL-2 in vitro, in addition to preventing intestinal bacterial translocation." (PMID 37161621, 2023). "Our results showed that HPE could inhibit the production of IL-4, IL-6, IL-13 and TNF-α released by mast cells, thus, ultimately, compromised mast cell-mediated allergic diseases." (PMID 38012745, 2023).
Allergy (continued). "In order to determine the inhibitory effect on de novo synthesized inflammatory mediators, including TNF-α, IL-6, IL-8, and IL-4 released during an allergic reaction, the HMC-1 cells were pre-treated with KHs for 1 h and followed by a 24 h of induction with PMACI." (PMID 37667314, 2023). "Inflammatory cytokines may promote allergic sensitization, as demonstrated for TNF-α, acting as an allergy adjuvant in airway models." (PMID 36483186, 2022). "However, no eye rubbing or scratching was observed during the period of allergy induction in our study, while elevated TNF-α, IL-1β, and IL-6 mRNA levels were still confirmed." (PMID 35692541, 2022). "In summary, it was speculated that MAPK 1, MAPK 10, MAPK 14 and TNF may be the key targets of PLP to treat allergy." (PMID 35879791, 2022). "Potential targets for developing new therapies for allergic diseases include IgE, TH2 lymphocytes and TH2-derived cytokines, IL-4 and IL-5, and activated mast cells releasing bioactive allergy mediators (histamine, tumor necrosis factor, prostaglandin D2, etc.)." (PMID 35447916, 2022). "Moreover, the important targets of MAPK 1, MAPK 10, MAPK 14 and TNF are mainly distributed in the FcεR I signal pathway that is related to allergic reaction (and the copyright of this KEGG pathway picture belongs to Kanehisa Laboratory)." (PMID 35879791, 2022). "Similarly, TNFR-1 as one of the two major receptors for TNF-alpha is a crucial protein in signal transmission from TNF alpha and activation of cellular pathways in many cells involved in the inflammation and allergy process." (PMID 33920429, 2021). "In addition, proinflammatory Th17 cells and inducible Th2 cells able to synthesize excessive TNFα amounts are upregulated during late stages of atopic conditions resulting in symptomatic allergies." (PMID 35011793, 2021). "Furthermore, ferulic acid inhibits TNF-α and IL-4 cytokine levels in IgE-dependent allergic disease experimental models." (PMID 34576749, 2021). "TNF-alpha activates Th2 cells and its increase was also shown in many allergic diseases." (PMID 33920429, 2021). "Currently, some medications including amino salicylates, glucocorticosteroids, immune modulators, antibiotics, and anti-TNF drugs are prescribed for IBD patients, which cause severe adverse effects such as increasing anti-antibody reactions, risk of allergy, infection, and mutagenesis." (PMID 32576228, 2020). "In addition, PL or germinated brown rice contains the polyphenolic compounds such as protocatechuic acid and gallic acid, which inhibited the expression of cytokines (TNF-α and IL-4) exerted by IgE-mediated allergy-induced basophils." (PMID 31871471, 2019). "Usage of TNF-α inhibitors, history of allergy, and serum hypercalcemia may be independent predictors of TB-IRIS in non-HIV patients." (PMID 31905985, 2019). "Moreover, these oligosaccharides were able to inhibit the secretion of allergy-related mediators like β-hexosaminidase, histamine and IL-4 and TNF-α." (PMID 30988664, 2019). "Furthermore, multivariate analysis revealed that usage of TNF-α inhibitors, history of allergy, and serum hypercalcemia were related to TB-IRIS." (PMID 31905985, 2019). "The most pivotal cytokines in an allergic reaction are IL-4 and TNF-α." (PMID 31829185, 2019). "Some cytokines such as TNF-α and IL-4 can be used as fascinating therapeutic target molecules for IgE-mediated allergic responses and proinflammatory Th2 cell responses in allergic diseases." (PMID 31871471, 2019). "In addition, activated RBL-2H3 cells induced the expression of inflammatory cytokines (tumor necrosis factor-α and interleukin-4), which are critical for the pathogenesis of allergic disease, through the activation of c-Jun N-terminal kinase (JNK)." (PMID 31195760, 2019). "However, animals exposed to antibiotic and sensitized with TNF-a + peanut antigen appeared to exhibit slightly higher allergy scores (at 15, 30 and 45 min) than control animals." (PMID 30410548, 2018).